TNF (tumor necrosis factor)
Diseases named in the same sentence as TNF in open-access papers (continued):
Sharing a sentence is not in itself a finding about the gene and the disease.
tumor (continued). "Using siRNA to CXCL8, we found that CXCL8 was significantly involved in mediating the pro-metastatic activities gained by TNFα-stimulated TNBC:MSC “Contact” co-cultures: angiogenesis, migration-related morphology of the tumor cells, as well as cancer cell migration and invasion." (PMID 31031757, 2019). "TRAIL has historically been distinct from the Fas ligand and TNFα in terms of selective apoptosis induction in tumor cells and has a nearly non-existent systemic toxicity." (PMID 31412671, 2019). "The authors showed that the tumor-cell-conditioned medium increased the percentage of M2 macrophages determined via RT-PCR and upregulated M2 polarization markers CD163, CD206, IL-10, and Arg1 while downregulating M1 marker TNFα." (PMID 31921102, 2019). "As an example, the presence of TNF, IL-1, IFN-γ and hypoxic conditions in the TME induces the secretion of proangiogenic and immune suppressive factors (including EGF, PDGF, fibroblast growth factor 2, FGF-2, VEGF, IL-6 and IL-10) allowing tumor proliferation." (PMID 30781344, 2019). "In addition, in 4T1 tumours with pre‐existing immune infiltrates, we compared the effect of TNFα and TNFα‐CSG on immune cell infiltration at the maximally tolerated dose for TNFα (5 daily injections of 0.5 μg)." (PMID 31709774, 2019). "After activation, CTL expresses FasL and TNF-α, binds to the Fas and TNFR1 on the surface of tumor cells, and generates FADD, which will conduct the apoptosis signal into the cell and perform CASP8 proteolytic activation, thus initiating the apoptosis process of tumor cells." (PMID 31905767, 2019). "This was confirmed by in vivo experiments on tumor-bearing mice, where the nanoparticles were able to induce IL-12 production which resulted in increased IFNγ and TNFα in the tumor milieu, thus tumor growth without any sign of systemic toxicity." (PMID 31662751, 2019). "Breast and gastric tumor-derived exosomes can induce a M1 pro-inflammatory response in macrophages through the activation of NFκB, which in turn stimulates production of inflammatory cytokines including GCSF, IL-6, IL-8, IL-1β, CCL2, and TNF-α." (PMID 31555295, 2019). "Similarly, mice that received anti-PD-1 showed a greater number of TNFα+ and IFNγ+ DNT cells in the tumor." (PMID 30857561, 2019). "In parallel, in the contact-dependent process, TNFα-driven activation of p65 - mainly in the tumor cells but also in the MSCs - has given rise to elevated Notch1 expression and activation." (PMID 31105691, 2019). "Of note, MDA-MB-231 cells grown in the presence of MSCs only or with TNFα alone did not migrate as well as tumor cells grown with MSCs and TNFα (Figure 9A2)." (PMID 31031757, 2019). "To further confirm that the low concentrations of dox used to culture primary tumor cells do not directly inhibit the NFκB pathway we treated NIH3T3 cells with TNFα in the presence or absence of 2 μg/ml dox and measured NFκB target genes." (PMID 30990165, 2019). "Diminished TNF-α production is suggestive of decreased anti-tumor activity in T cells, although T-cell TNF-α production does not appear to be mediated by STAT4 in our experimental HNSCC model." (PMID 32010142, 2019). "Further evidence that IR-780 induced a more pronounced effector phenotype was attained by the assessment of multiple CTL effector markers through real-time qPCR of the whole tumor mRNA, demonstrating increased expression of IFN-γ, TNF-α, Granzyme B, EOMES, Perforin, BLIMP-1, FOXO3, and CXCL10." (PMID 31781498, 2019). "These include direct effects on tumor cells by cytokines produced by CD4+ T cells such as IFN-γ, TNF-α, and IL-2, modulation of DCs and other antigen presenting cells in the tumor microenvironment as well as direct killing of tumor cells by cytolytic CD4+ cells." (PMID 31379821, 2019). "The anti-tumor effects of Th1 cells may reflect their known role in enhancing CD8+ T cell responses and activating macrophages, through the secretion of TNF-α and IFN-γ." (PMID 30127783, 2018).
tumor (continued). "Additionally, NK cells can directly kill cancer cells, secrete IFNγ, TNF, GM-CSF, and other cytokines to promote CD8 T cell and APC activity, while also controlling tumor metastasis and recognizing CD8 T cell-resistant tumors with downregulated MHC I36." (PMID 29686284, 2018). "Clinically, elevated TNFα serum levels have been detected in patients with a wide range of tumor types, although TNFα is not universally detectable." (PMID 29946544, 2018). "Following chemo- and radiotherapy, stressed and dying cancer cells release a variety of substances, including reactive oxygen as well as nitrogen species along with cytokines, such as IL-6, IL-8, and TNF-α, which can activate PAFR agonist production in the tumor microenvironment 14,58,59." (PMID 30328954, 2018). "In addition, NK cells can release pro-inflammatory cytokines and various chemotactic factors (IFNγ, TNFα, GM-CSF, CCL3/CCL4) potentially amplifying immune responses to the tumor." (PMID 30459756, 2018). "On the other hand, a wide range of pro-inflammatory factors, e.g., PGE2, TNF, IL-1β, IL-6, S100A8, S100A9, IFNγ, IL-4, IL-10, and IL-13 secreted by cancer cells and leukocytes residing in the tumor inhibit the differentiation of myeloid progenitors and enhance their suppressive capacity." (PMID 30349530, 2018). "Strikingly, transplantation of Egr-wild-type immune cells could rescue the progression of scrib, Rasv12 tumours, as well as JNK activation, providing the final demonstration that Drosophila TNF shares protumour effects with its mammalian counterpart." (PMID 29725601, 2018). "Further work has shown that cytokines play a role in the regulation of complement inhibitory protein expression, and in particular, IFN-γ, TNF-α, IL-1β (IL1B), and TGF-β (TGFB) have been found to upregulate complement regulatory proteins in cultured tumor cells." (PMID 30473747, 2018). "Although EET receptors have not been fully identified, multiple pathways, including the GPCR/PPAR/RXR, VEGF, EGFR, tumor necrosis factor α (TNFα) and matrix metalloproteinase (MMP) pathways, are involved in the mechanism through which EETs stimulate tumor growth, angiogenesis and metastasis." (PMID 30242145, 2018). "The cytokine profile identified in the ACP RNA-Seq dataset, in particular the significantly higher expression of IL1A (18.1-fold), IL18 (14.8-fold), TNF (10.4-fold) and IL1B (7-fold) in human ACP tumours relative to controls, was suggestive of inflammasome activation [Suppl." (PMID 29541918, 2018). "We further detected 20 serum cytokines in tumor-bearing mice and 7 cytokines were significantly different between GLE treated and model groups, including IFN-γ, IL-1β, IL-4, IL-9, IL-12, RANTES and TNF-α." (PMID 30139984, 2018). "This indicates that it is not the tumor cells which depend on TNFα signaling, but rather immune cells derived from the bone marrow." (PMID 30591653, 2018). "In the past decades, lots of researchers have focused on the modifications of TNFα structure so as to increase its anti-tumor activity, although these modifications are not remarkably effective." (PMID 29506556, 2018). "This corresponds to a greater induction of IFN-gamma, TNF-alpha and IL-2 in response to MOLM-14 as compared to HL-60 tumor cells, and a greater induction in response to HL-60 vs. KG-1a, and also correlates with the relative cytotoxic activity of the anti-CD33 CARs against these cell lines." (PMID 30524966, 2018). "As an anti-tumor agent, TNF-α induces cancer cell death, and KLT also has anti-tumor effects." (PMID 29467927, 2018). "Likewise, we also showed that TNFα up-regulate genes CLDN-1, IL6, and NFκBIA, which have previously been reported to increase OSCC cell proliferation, supporting our increased tumor volume findings." (PMID 30018735, 2018).
tumor (continued). "In the present study, we show that GD2.BBζ CAR-T cells could preferentially secrete high levels of Th1 cytokines, including IL-2, TNF-α, and IFN-γ, upon encountering a tumor cell and exert strong antitumor activity in vitro." (PMID 29298689, 2018). "Interestingly, blocking TNFR2 is sufficient to diminish TNF-evoked cell growth, indicating TNFR2 as more important for tumor progression than the activation of signal kinases including p42/p44 MAPK, JNK, and AKT via the ubiquitous TNFR1." (PMID 29892300, 2018). "Conversely, in THP-1 cells, the decrease in TNF-α, IL-6 and IL-1β levels by WRE may prevent excessive activation of NF-κB, diminish cytokine induced tumour immunosuppressive activity and cancer progression." (PMID 29631586, 2018). "Tumor-associated macrophages play a role in β-adrenergic signaling pathways, by accelerating angiogenesis, chemokine secretion to attract tumor cells, secretion of pro-inflammatory cytokines (IL-1, IL-6, IL-8, and tumor necrosis factor (TNF)-α) and escape of anti-tumor responses." (PMID 29334991, 2018). "In contrast to the effect of TGFβ in combination with the K562 feeder cells, IL-2 plus TGFβ alone did not enhance the anti-tumor IFNγ and TNFα production, in agreement with what has been previously reported." (PMID 30400618, 2018). "TNF-α levels in two groups of tumour carriers were not significantly different from those seen in the intact mice." (PMID 29609556, 2018). "In a first phase (elimination phase), the stimulated immune system produced many costimulating cytokines (TNFα, IL1, IFNα, TLR, ICAM1, IL2, IL12, IFNγ,) and less inhibitors (IL10, IL4, IL13, PD1/PD-L1, prostaglandins, LAG-3, TGFβ) resulting in efficient tumor cell killing." (PMID 29492219, 2018). "Despite the anti-cancer properties of TNF-α, elevated levels of TNF-α are not always capable of destroying all abnormal cells and, paradoxically, they can cause severe symptoms related to tumor occurrence." (PMID 30518097, 2018). "Hoshida and colleagues showed that pro-inflammatory gene expression (TNFα, IL-6, and nuclear factor-κB) in the NTME, rather than the tumor itself, strongly associated with poor prognosis and high recurrence rate in patients undergoing hepatic resection." (PMID 30150983, 2018). "T-cell lines generated from PCa patients using the agonist peptide showed high levels of lysis of PAGE4-expressing tumor cells and enhanced secretion of Interferon gamma (IFN-g), granzyme B, Tumor Necrosis factor alpha (TNF-a), Interleukin 2 (IL-2) and lymphotactin." (PMID 29914187, 2018). "Only the cytokines GM-CSF, IFN-γ, IL-2, IL-4 and TNF-α were detected at relevant concentrations in the presence of UniCAR CD28/ζ-armed T cells, tumor cells and TM substantiating that cytokine secretion occurs in a strictly TM- dependent- and target-specific manner." (PMID 29484126, 2018). "Similar to the results obtained with MMDCs, ss-EEV fractions and TNFα-EEV fractions but not EEV-free supernatant increased the directional transwell transmigration of tumor cells by 2.59-fold and 7.26-fold, respectively." (PMID 29650776, 2018). "While there was no obvious influence of TNF‐α on the viability of tumour cell, the expression level of miR‐130b in target cell mounted in response to the increase in the TNF‐α concentration." (PMID 29632814, 2018). "As expected, we found the activation of the TNF‐α/NF‐κB axis, and the knockdown of TNFR1, RelA, RelB, c‐Rel, and CUL4B showed similar effects on the proliferation, invasion, colony formation, and the in vivo tumor forming ability of cells." (PMID 29377600, 2018). "However, many tumor cell lines and primary tumors are resistant to DR5 targeted agents including recombinant tumor necrosis factor (TNF)-related apoptosis-inducing ligand (TRAIL) and anti-DR5 agonistic antibodies." (PMID 30613368, 2018).
tumor (continued). "Therefore, a positive feedback loop has been suggested where in CXCL12 induced TNF-α potentially acts on the cancer cells and induces CXCR4 expression thereby enhancing tumor cell migration." (PMID 30061485, 2018). "Furthermore, we confirmed our data in xenograft tumor tissue, and the results showed that IL-8, TGF-α and TNF-α were attenuated in UHRF1 suppressed group." (PMID 30174788, 2018). "For example, IL-33 activates NK cells which could direct kill tumor cells, and could also induce the release of anti-tumor cytokines, such as IFN-γ and TNF-α." (PMID 30112116, 2018). "Tumor necrosis factor-alpha (TNF-α) is a critical pro-inflammatory cytokine that has been shown to play an important role in many physiological and pathological processes, including immunity, cachexia, inflammatory reaction, and tumor progression." (PMID 29467927, 2018). "Deficiency of Eomes in T cells also dampened effector cytokine (IFN-γ and TNF-α) production and cytotoxicity (marked by surface CD107a expression and Granzyme B production) of CD8+ T cells in the tumor, although effector functions of CD8+ T cells in spleen and TDLN was not affected." (PMID 30619337, 2018). "Tumors after TNFα GET were larger and contained low levels of infiltrating lymphocytes, while after IL-12 GET monotherapy or combined treatment, H&E staining showed extensive infiltration of lymphocytes in the tumor site." (PMID 29468364, 2018). "Promising tumour regression was reported after synergistic effects of a mitotic inhibitor acting on PLK1 (BI2536) to induce mitotic arrest, and a proapoptotic agent (LCL161) to sensitize HCC cells to TNFα-triggered cell death in a murine model of HCC." (PMID 30662724, 2018). "NF-κΒ activation is a reciprocal response to various anti-tumor reagents, and TNF-α is no exception." (PMID 29467927, 2018). "Among a group of genes responsible for cell contact independent mechanism of tumor promotion and reportedly impacting on cancer progression, IDO and IL-6 genes were the only ones consistently overexpressed in PCa cells upon stimulation with IFN-γ or TNF-α." (PMID 29896191, 2018). "The results of this study showed that S180 tumor-bearing slightly increased hepatic TNF-α and decreased IL-10 levels, but no statistical difference." (PMID 29950302, 2018). "We show that the IL-33/ST2 interaction is necessary for SCC progression, that it is involved in a mechanism during the recruitment of CD4+ T lymphocytes, dendritic cells, and macrophages in the tumor microenvironment, and that it promotes the production of IFN-γ, TNF-α, IL-10, and IL-17." (PMID 30112116, 2018). "Additionally, hypoxic condition also promotes high ROS in the tumour microenvironment, subsequently leads to the activation of stress signalling in CSC mediated by TGF-β and TNFα signalling pathway that maintain their undifferentiated state." (PMID 29506506, 2018). "The CD137 ligand (CD137L) is a member of the tumor-necrosis factor (TNF) superfamily that binds CD137 to provide co-stimulatory signals for T-cell activation, and has been shown to have anti-tumor effects in a number of models when it binds to CD137 receptors to induce costimulation on T-cells." (PMID 29295974, 2018). "Tumor tissues from a2Vfl/flMMTVCre mice showed significantly higher numbers of TNF‐α‐positive cells compared to control (P = 0.007), confirming an increased necrosis in tumor microenvironment in the absence of a2V." (PMID 29178186, 2018). "Potentially elevated secretion of IL6 and TNF by Snail-expressing cancer cells can therefore not explain the observed Dlk1-Dio3 locus repression in tumor-infiltrating immune cells." (PMID 30190790, 2018). "In addition, silencing PD-L1 or PD-L2 specifically on DCs enhanced proliferation of tumor-specific CTLs and CD4+ T-cells, augmented production of IFN-γ, tumor-necrosis factor alpha (TNFα), IL-2, IL-5, and IL-12 and promoted cytolysis of tumor cells in vitro." (PMID 30568653, 2018).
tumor (continued). "There has been no previous study regarding the association between DII and tumor size or lymph node status, but DII has been shown to associate with inflammatory cytokines such as IL-6 and TNF-α." (PMID 30111758, 2018). "All together, evidence shows that TNF-α-dependent activation of systemic Toll signalling is an important component of a nonautonomous tumour suppressor program." (PMID 29725601, 2018). "Importantly, increases in TNFα, IL-12p70 and IL-2 are not merely consequent of enhanced immune cell presence, as a number of other cytokines were unaltered by ibuprofen treatment including those associated with tumor associated macrophages, monocytes and M2 polarized macrophages [IL-4, IL-6, IL-10]." (PMID 30285905, 2018). "In the tumor microenvironments, there are not only IFN-γ, TNF-a, and GM-CSF which could activate macrophages like M1 macrophages, but also IL-4, IL-10 and CSF-1 which induce M2 macrophages differentiation." (PMID 30180849, 2018). "SLRPs can bind collagens and other matrix components; modulate immune cells by TLR, tumor necrosis factor-alpha (TNFα), and TGF-β pathways; and influence tumor growth and matrix remodeling by interaction with growth factors to modulate cellular differentiation and proliferation." (PMID 29970158, 2018). "The levels of two pro-inflammatory cytokines, interferon gamma (IFN-γ) and tumor necrosis factor alpha (TNF-α), are significantly reduced in tumor microenvironments containing CD8+LAG-3+PD-1+ T-cells compared with those in the tumor milieu containing LAG-3+ or PD-1+CD8+ T-cells." (PMID 30271341, 2018). "In addition to EV-embedded cytotoxic miRNA, death molecule ligands such as FasL, TNF-α and PD-L1 on CD8+ T cell EVs are candidates for depletion of tumour stromal mesenchymal cells." (PMID 29382847, 2018). "Our results showed that the TMZ-resistant subline had lower levels of TNF-α-induced VCAM-1 than that of the parental U251 cells, which may benefit the tumor microenvironment by achieving immune evasion." (PMID 29301329, 2018). "Importantly, the GLPS and triterpene acid were demonstrated to promote the production of cytokines, such as IL-1β, IL-4, IL-6, IL-12, IL-17, RANTES, TNF-α and IFN-γ, and thus to exhibit immuno-modulation and anti-tumor activities." (PMID 30139984, 2018). "Overexpression of TNF in cancer cells results in longterm tumor growth suppression, independent of IL-12 or IL-18 and works via a STAT1 and IFN regulatory factor 1-dependent IFN-gamma pathway." (PMID 30170620, 2018). "In opposite, western blotting analysis results showed clearly that resveratrol alone or in combination with 5-FU or with TNF-β or with TNF-α substantially down-regulated the mentioned proteins expression in both HCT116 and HCT116R cells in alginate tumor microenvironment cultures." (PMID 30002278, 2018). "Wound healing and Matrigel assays revealed that IRF-1 and XAF1 strongly suppresses TNF-induced tumor cell migration and invasion and this effect is abrogated by depletion of XAF1 and IRF-1, respectively, indicating TNF-driven tumor malignancy is impaired by the IRF-1−XAF1 interplay." (PMID 30042418, 2018). "In addition, the infiltrated OT-I and OT-II cells in the B16-OVA tumor produced remarkably higher levels of IFN-γ and TNF-α compared to the singular treatments." (PMID 28423736, 2017). "SUP3 was shown to enhance cross-presentation by CD8+ cDCs in vitro, up-regulate the expression of CD40 and CD86 co-stimulatory molecules and induce production of IL-6 and TNFα in DC, culminating in an antigen-specific CD8+ T cell response and increased immunization against tumor challenge." (PMID 29050360, 2017). "TNF-α and IFN-γ are significant inflammatory cytokines affect tumor growth." (PMID 29268703, 2017). "The concentrations of compound 7 required to stimulate production of TNF-α release were not significantly correlated with those required for RAP1A inhibition nor were tumor cell growth inhibition and RAP1A inhibition correlated." (PMID 28729550, 2017).